RXRA (retinoid X receptor alpha)
Diseases named in the same sentence as RXRA in open-access papers (continued):
Sharing a sentence is not in itself a finding about the gene and the disease.
neuropathy (3 papers, 2024 to 2025). A disorder affecting the nervous system that manifests with pain, tingling, numbness, and/or muscle weakness. "Two other variants (rs917778 of the MVB12B and rs2234753 of the RXRA genes) appeared to have a protective effect against neuropathy, reducing the risk to 0.07–0.08." (PMID 38339094, 2024). "At this time, rs604349 in MYBPHL and rs2032930/rs2032931 in the RMI2 gene appear to be of importance in increasing the risk for developing neuropathy, while rs917778 in MVB12B and rs2234753 in the RXRA gene might reduce the likelihood of this complication." (PMID 38928135, 2024).
ovarian carcinoma (3 papers, 2018 to 2022). A malignant neoplasm originating from the surface ovarian epithelium. "Increased expression of RXRα and Sirt1 was associated with increased survival rates in advanced stages of ovarian cancer." (PMID 34870752, 2022). "Our report shows that the expression of nuclear RXRα and Sirt1 in advanced ovarian cancer is significantly associated with longer overall survival." (PMID 34870752, 2022). "RSV, which induces apoptosis and decreases proliferation in human ovarian cancer cell lines, was associated with decreased expression of Sirt1 in mucinous ovarian cancer and increased expression of RXRα in mucinous, carboplatin resistant ovarian cancer cells." (PMID 34870752, 2022). "In the present study, we evaluated RXRα inhibited resveratrol-stimulated apoptosis of ovarian cancer cells." (PMID 34870752, 2022). "Sirt1 and RXRα expression was analyzed in 123 cases of ovarian cancer (110 serous and 13 mucinous cases)." (PMID 34870752, 2022). "In conclusion, we observed that the combination of nucleus RXRα and Sirt1 expression was correlated with increased overall survival in late-stage ovarian cancer." (PMID 34870752, 2022). "This study aimed to analyze RXRα and Sirt1 as potential therapeutic targets in ovarian cancer." (PMID 34870752, 2022). "We tested the involvement of Sirt1 and RXRα in RSV-induced apoptosis in ovarian cancer cell lines." (PMID 34870752, 2022). "Our results suggest that RXRα could play an important role in the regulation of apoptosis in human ovarian cancer." (PMID 34870752, 2022). "RXRα expression correlates withpoor prognosis in ovarian cancer patients." (PMID 35404047, 2022). "Despite several papers that mentioned a special role of RXRα receptor in resistance mechanisms, maximum resistance to retinoic acid was shown in ovarian cancer cell lines with downregulation of both RARα and RXRα in contrast to cell lines with reduced levels of either RARα alone or RXRα alone." (PMID 29301374, 2018). "In the present study, we immunohistochemically examined the expression of RXRα and Sirt1 in mucinous and serous ovarian cancer and analyzed the relationship between RSV, RXRα and Sirt1 in ovarian cancer in vitro." (PMID 34870752, 2022). "A total of 114 cases of ovarian cancer expressed RXRα in the nucleus with a median of 2, 4 did not express RXRα at all and 5 cases were not evaluable." (PMID 34870752, 2022).
pancreatic cancer (3 papers, 2013 to 2020). "When analyzed by genotype, a few SNPs in CASR and RXRA were associated with pancreas cancer risk; however, only one was significant in the log-additive models." (PMID 23826131, 2013). "SNPs in the CYP24A1, CYP2R1, calcium sensing receptor (CASR), vitamin D binding protein (GC), retinoid X receptor-alpha (RXRA) and megalin (LRP2) genes were significantly associated with pancreas cancer risk." (PMID 23826131, 2013). "Furthermore, RXRα promotes the proliferation and inhibits the apoptosis of pancreatic cancer cells through TGF‐β/Smad pathway." (PMID 33128348, 2020).
schizophrenia (3 papers, 2010 to 2019). A major psychotic disorder characterized by abnormalities in the perception or expression of reality. "The chromosomal region containing RXRA, 9q34, has been associated with schizophrenia." (PMID 20064257, 2010). "The current findings showing that expression of RXRA, PPARA and PPARB/D is abnormally reduced in the hair-follicle cells of patients with schizophrenia not only support their putative role in schizophrenia pathogenesis but also suggest that this measure is a potential biomarker for schizophrenia." (PMID 28872641, 2017).
Sepsis (3 papers, 2022 to 2024). Sepsis is defined as life-threatening organ dysfunction caused by a dysregulated host response to infection. "It has been confirmed that RXRα can inhibit the inflammatory response by inhibiting the release of proinflammatory factors, so as to protect against hypotension and tachycardia caused by sepsis." (PMID 36555577, 2022). "Our data suggest that the loss of hepatic HNF4α impairs the expression of several other nuclear receptors besides PPARα, including RXRα, FXR, CAR, AR and LXRα, and therefore has a broad downstream impact in sepsis." (PMID 39261648, 2024). "The reduced expression of RXRα, FXR and LXRα in sepsis has already been described." (PMID 39261648, 2024). "The downstream effects of HNF4α failure in sepsis has a strong effect on PPARα levels and consequent PPARα-mediated FFA consumption, as well as on the expression of several other nuclear receptor TFs in the liver, such as Liver X receptor-α (LXRα), RXRα and Farnesoid X receptor (FXR)." (PMID 39261648, 2024).
triple-negative breast carcinoma (3 papers, 2020 to 2022). An invasive breast carcinoma which is negative for expression of estrogen receptor (ER), progesterone receptor (PR), and human epidermal growth factor receptor 2 (HER2). "DANCR-induced RXRA phosphorylation suppressed RXRA-inhibited PIK3CA transcription in triple negative breast cancer cells and ultimately activated the downstream PI3K/AKT signaling." (PMID 33123287, 2020). "A recent study uncovered a direct impact of RXRα in the TGF-β-dependent regulation of the CCL2 gene in triple-negative breast cancer cells, indicating that physical interaction might occur between these proteins." (PMID 36078038, 2022).
acute promyelocytic leukemia (2 papers, 2013 to 2018). An aggressive form of acute myeloid leukemia (AML), characterized by arrest of leukocyte differentiation at the promyelocyte stage, due to a specific chromosomal translocation t(15;17) in myeloid cells. "Research has shown that binding of RXRα to PML–RARα is essential in the development of acute promyelocytic leukemia in transgenic mice, further illustrating the carcinogenicity of RXRα when it functions inappropriately." (PMID 30093910, 2018). "The relevance of RXRα in cancer is well-established as genetic disruption of RXRα can promote tumorigenesis and RXRα binding to PML/RAR is necessary for the development of acute promyelocytic leukemia." (PMID 23875171, 2013).
alopecia (2 papers, 2017 to 2022). Hair loss usually from the scalp. "The mutant mice without RXRA developed hair follicle degeneration, then alopecia." (PMID 35413801, 2022). "Therefore, the result of interaction with the RXRα without ligand binding gives profitable information to understand each mutant with regard to occurring alopecia." (PMID 28698609, 2017).
Alzheimer disease (2 papers, 2010 to 2023). A progressive, neurodegenerative disease characterized by loss of function and death of nerve cells in several areas of the brain leading to loss of cognitive function such as memory and language. "Observed changes in gene expression were isoform-specific with more robust Alzheimer's disease (AD)-associated changes observed in RXRα levels." (PMID 20843353, 2010). "Furthermore, RXRA may potentially increase people’s risk of developing Alzheimer’s disease by affecting brain cholesterol metabolism." (PMID 38147020, 2023).
asthma (2 papers, 2011 to 2019). "In this study, we report an analysis of association between single nucleotide polymorphisms (SNPs) in TSLP, OX40L, IL7R, and RXRα and AR in three independent studies of children with asthma from Costa Rica, North America, and Sweden." (PMID 21244681, 2011). "We genotyped 15 single nucleotide polymorphisms (SNPs) in TSLP, OX40L, IL7R, and RXRα in three independent cohorts: 592 asthmatic Costa Rican children and their parents, 422 nuclear families of North American children with asthma, and 239 Swedish children with asthma." (PMID 21244681, 2011). "SNPs in OX40L, IL7R, and RXRα were not consistently associated with AR in children with asthma." (PMID 21244681, 2011).
bladder urothelial cancer (2 papers, 2018 to 2022). "This included SPOP, which was exclusively mutated in prostate adenocarcinoma, and RXRA, where 80% of mutations were observed in the bladder urothelial cancer." (PMID 29572294, 2018).
breast ductal carcinoma in situ (2 papers, 2008 to 2014). "RXR isotypes are overexpressed in 66% of breast ductal carcinoma in situ lesions and RXRα upregulation was found to be associated with malignant transformation." (PMID 25013807, 2014).
cholangiocarcinoma (2 papers, 2020 to 2022). A carcinoma that arises from the intrahepatic biliary tree (intrahepatic cholangiocarcinoma) or from the junction, or adjacent to the junction, of the right and left hepatic ducts (hilar cholangiocarcinoma). "The decrease in FXR and RXRα expressions observed in this study was in accordance with human cholangiocarcinoma datasets from Oncomine and TCGA." (PMID 31964941, 2020). "FXR and RXRα expressions were significantly reduced, which were similar to that observed in cholangiocarcinoma in TCGA and Oncomine databases." (PMID 31964941, 2020). "Decreased FXR and RXRα RNA expression was also found in human cholangiocarcinoma (CHOL) dataset in the TCGA database." (PMID 31964941, 2020).
colorectal tumor (2 papers, 2016). "Inhibition of miR-193a expression by Max and retinoid X receptor alpha (RXRα) activates KRAS expression to promote colorectal tumor growth." (PMID 27007150, 2016). "In summary, we found that RXRα expression was decreased in malignant human colorectal tumors." (PMID 27167203, 2016).
cutaneous melanoma (2 papers, 2017 to 2022). A primary melanoma arising from atypical melanocytes in the skin. "We have previously shown that keratinocytic RXRα has a role in acute UV-induced melanocyte proliferation, in chemically induced melanomagenesis and in cutaneous melanoma formation when combined with mutant Cdk4 by chemical carcinogenesis." (PMID 29121869, 2017).
cutaneous T-cell lymphoma (2 papers, 2014 to 2025). "In the RXR transfection assay Bexarotene (LG1069), a rexinoid approved for treating cutaneous T-cell lymphoma, displayed an EC50 of 18nM for activation of RXRα." (PMID 25143786, 2014).
endometritis (2 papers, 2021 to 2025). An acute or chronic, usually bacterial infectious process affecting the endometrium. "For example, RXRA and RXRG mRNA expression was significantly higher in the endometrial tissue of normal cows compared to repeat breeder cows and repeat breeder cows with subclinical endometritis." (PMID 40564281, 2025).
fibroids (2 papers, 2007 to 2019). "An example is the switching of the ubiquitin/proteasome-dependent degradation of RXRα by phosphorylation in leiomyomas." (PMID 31100862, 2019).
fibrosis (2 papers, 2015 to 2022). the formation of excess fibrous connective tissue in an organ or tissue in a reparative or reactive process. "We also observed a significant increase in miR-654-5p expression and downregulation of RXRα in the CCl4-induced fibrosis mouse model." (PMID 35465330, 2022).
hepatitis B (2 papers, 2016 to 2022). "This importance of RXRA using an epistasis network framework has been supported by traditional approaches that implicate variants in the RXRA gene in immune response to hepatitis B, measles, and rubella vaccines." (PMID 27513748, 2016).
hyperlipidemia (2 papers, 2024 to 2025). "During the process of lipid regulation in zebrafish, the downregulation of Pparγ and Rxrα positively impacted zebrafish hyperlipidemia." (PMID 38474201, 2024).
hypothyroidism (2 papers, 2005 to 2021). Abnormally low levels of thyroid hormone. "Since TRβ1 functions as a heterodimer with RXRα, these findings might explain some features of hypothyroidism and thyroid hormone resistance commonly found in CRF patients." (PMID 15807894, 2005).
intestinal tumor (2 papers, 2015). "Moreover, this study detected a green tea-mediated rise in protein and transcript levels of retinoid X receptor alpha (RXRa), which was found to be selectively downregulated in intestinal tumours of control mice." (PMID 26161152, 2015). "In this study, using the APCMin/+ intestinal tumor mouse model, we demonstrated downregulation of RXRα expression, which may complement the disabled APC-dependent proteasomal degradation pathway to increase β-catenin accumulation in 56Fe-induced tumors." (PMID 26500891, 2015).
keratoconus (2 papers, 2017 to 2018). A degenerative, structural disorder of the eye, characterized by a cone-shaped protrusion of the cornea. "Another keratoconus gene is RXRA, which encodes a nuclear retinoic acid receptor protein." (PMID 28676647, 2017). "For example, FOXO1, RXRA and FNDC3B are the 3 genes that showed genome-wide significant association with keratoconus." (PMID 28676647, 2017).
kidney injury (2 papers, 2022 to 2025). Trauma to the kidney. "Activation of RXRα by bexarotene, an FDA-approved RXRα agonist, restores the chromatin state and gene expression program to protect TECs against severe kidney injury." (PMID 36443310, 2022).
liver cirrhosis (2 papers, 2018 to 2022).
lung adenocarcinoma (2 papers, 2021 to 2024). A carcinoma that arises from the lung and is characterized by the presence of malignant glandular epithelial cells. "In lung adenocarcinomas, a high expression of RXRα significantly (p = 0.0031) correlated with the probability of increased survival." (PMID 34638488, 2021). "In lung adenocarcinomas, the level of RXRα mRNA was significantly (p = 0.0017) lower in the cancer tissue compared to adjacent normal tissue in the 57 paired samples available." (PMID 34638488, 2021).
osteoarthritis (2 papers, 2018 to 2021). A noninflammatory degenerative joint disease occurring chiefly in older persons, characterized by degeneration of the articular cartilage, hypertrophy of bone at the margins and changes in the synovial membrane. "Osteoarthritis (OA), a most common and highly prevalent joint disease, is closely associated with dysregulated expression and modification of RXRα." (PMID 34417523, 2021). "Here, we reported that RXRα modulator K‐80003 prevented inflammatory and destructive responses in a rat model of osteoarthritis." (PMID 34417523, 2021).
prostate adenocarcinoma (2 papers, 2018 to 2025). "12-O-tetradecanoylphorbol 13-acetate induces the formation of a heterodimer of NR4A1 with RXRα (NR4A1/RXRα heterodimer), leading to the translocation of NR4A1/RXRα heterodimer to mitochondria in the human prostate adenocarcinoma cell line LNCaP." (PMID 40746844, 2025).
psoriasis (2 papers, 2018 to 2024). An autoimmune condition characterized by red, well-delineated plaques with silvery scales that are usually on the extensor surfaces and scalp. "Epidermal Ki-67 and CK17 immunoexpression markedly increased in psoriasis compared to normal skin, (**p< 0.01) according to previous studies, whereas RXRα and CK1 expression decreased (**p<0.05)." (PMID 30613363, 2018). "Retinoic acid receptor RXRα, also known as NR2B1, is essential for retinoid drugs such as acitretin to treat severe psoriasis, adapalene to treat acne vulgaris, and alitretinoin to treat chronic hand eczema and psoriasis." (PMID 39798999, 2024). "Beside the alteration of psoriasis biomarkers, we documented in imiquimod-treated mouse CRBPI-knockout skin a more evident reduced expression of other retinoid binding proteins, such as CRABPII and RXRα." (PMID 30613363, 2018).
renal carcinoma (2 papers, 2010 to 2020). A carcinoma arising from the epithelium of the renal parenchyma or the renal pelvis. "RXRA on the other hand may play a critical role in vitamin D activity, particularly from dietary sources, since this gene has been shown to regulate cholesterol, which is abundant in eggs and yogurt, the food groups found statistically associated with renal cancer risk in this study." (PMID 20049159, 2010). "We therefore investigated whether common genetic variation in VDR and RXRA, the two genes we observed to be significantly associated with RCC risk, modified associations between renal cancer risk and the frequency of dietary intake of vitamin D and calcium rich foods." (PMID 20049159, 2010).
rhabdomyosarcoma (2 papers, 2015 to 2017). A rare aggressive malignant mesenchymal neoplasm arising from skeletal muscle. "Since retinoic acid receptor alpha and retinoid X receptor alpha were found to be novel targets of miR-27a, suggesting a potential role of miR-27a in therapy of rhabdomyosarcoma." (PMID 25915942, 2015). "We thus decided to experimentally test if RXRA is a target of miR-27a in the rhabdomyosarcoma cell line and found a marked decrease in RXRA expression levels in miR-27a overexpressing 293T cells, 24h post-transfection, when measured by qRT-PCR." (PMID 25915942, 2015). "MiR-27a contributes to rhabdomyosarcoma cell proliferation by suppressing RARα and RXRα." (PMID 29137318, 2017). "We demonstrated that miR-27a is implicated in cell cycle control by targeting the retinoic acid alpha receptor (RARA) and retinoid X receptor alpha (RXRA), suggesting a potential role of miR-27a in drug therapy of rhabdomyosarcoma." (PMID 25915942, 2015). "MicroRNA-27a contributes to rhabdomyosarcoma cell proliferation by suppressing RARA and RXRα." (PMID 29137318, 2017).
sarcopenia (2 papers, 2024). Progressive decline in muscle mass due to aging which results in decreased functional capacity of muscles. "Consistently across the three outcomes, RXRA, MDM1, RBL2, KCNJ2, and ADHFE1 were identified as risk factors, while NMB, TECPR2, MGAT3, ECHDC2, and GINM1 were identified as protective factors, all with potential as biomarkers for sarcopenia progression." (PMID 39409102, 2024).
Stroke (2 papers, 2019 to 2022). Sudden impairment of blood flow to a part of the brain due to occlusion or rupture of an artery to the brain. "Together, these observations establish key role of RXRα in determining the stroke-mediated damage and beneficial effects of pharmacological modulation of RXR in imparting protection against these deficits." (PMID 35015251, 2022). "Bexarotene treatment was able to rescue the post-stroke recuperation in control but not in the RXRα-ablated animals." (PMID 35015251, 2022).
Tetralogy of Fallot (2 papers, 2016 to 2019). A congenital cardiac malformation comprising pulmonary stenosis, overriding aorta, ventricular septum defect, and right ventricular hypertrophy. "Disruption of RXRα was recently associated with the cardiac malformation tetralogy of Fallot, previously associated with mutations in NKX2-5." (PMID 27683156, 2016). "Methylation of RXRA gene promoter may be one of the reasons for the downregulation of the expression of right subventricular bundle myocardium in patients with tetralogy of Fallot." (PMID 31772600, 2019).
ulcerative colitis (2 papers, 2017 to 2023). An inflammatory bowel disease involving the mucosal surface of the large intestine and rectum. "Expression of the nuclear receptors RXRα and PPARα was decreased in inflamed colonic-mucosa of ulcerative colitis patients and in IL-1β-treated Caco2-BBE cells." (PMID 28223944, 2017).